IL2 (interleukin 2)
Diseases named in the same sentence as IL2 in open-access papers (continued):
Sharing a sentence is not in itself a finding about the gene and the disease.
ovarian carcinoma (continued). "Vlad AM, Budiu RA, Lenzner DE, Wang Y, Thaller JA, Colonello K, Crowley-Nowick PA, Kelley JL, Price FV, Edwards RP: A phase ii trial of intraperitoneal interleukin- 2 in patients with platinum-resistant or platinum-refractory ovarian cancer." (PMID 30400835, 2018). "Specifically, Tregs inhibit the proliferation of CD8+ T cells as well as their production of IFNγ and IL-2, counteract the protective effect of cytotoxic T cells in ovarian cancer tissues, thus reversely correlated with patient survival." (PMID 28929459, 2018). "Among the suppressive mediators in ovarian cancer-associated ascites, the presence of EOC cells seems to play a role in the impairment of NK cells’ response to IL-2 stimulation." (PMID 28513532, 2017). "In this same ovarian cancer model, IL-2 treatment was shown to up-regulate CCR4 as well as CXCR4, which further enhanced the ability of Treg to migrate to the tumor microenvironment based on its elevated levels of the Treg ligands CCL22 and CXCL12." (PMID 22112546, 2011). "In our mouse model of ovarian cancer, tumor regression was entirely dependent on IL-2/IL-15 signaling." (PMID 21203522, 2010). "A patient with Stage IIIC, relapsed ovarian cancer received the highest dose of DAB/IL2 (12 μg/kg) and experienced a marked reduction in the ovarian cancer marker, CA-125, four weeks after a single infusion (from 121 U/ml to 38 U/ml)." (PMID 18334033, 2008). "The effect of DAB/IL2 on both peripheral blood Treg cell concentration and tumor burden has been previously examined in 4 patients with metastatic breast, lung or ovarian cancer (single infusion; 9 μg/kg or 12 μg/kg)." (PMID 18334033, 2008). "Moreover, CTLA-4 blockade has also been found to improve the anti-cancer effect of TILs by increasing TIL proliferation, proportion of CD8 + T cells and TIL immunoreaction, in ovarian cancer cells, compared to co-culture of IL-2 and TILs." (PMID 41024300, 2025). "Another promising yet challenging area of immunotherapy in ovarian cancer is cytokine therapy, which aims to enhance the immune response by administering or modifying specific cytokines, such as IL-2, IL-12 and IL-15, that activate natural killer (NK) and cytotoxic T lymphocytes." (PMID 40722601, 2025). "identifier: NCT01105650) enrolled 14 ovarian cancer patients, which were infused with haploidentical IL-2 activated NK cells followed by SC IL-2 infusion three times per week for fourteen days, after which NK cell expansion was detected in the peripheral blood of patients." (PMID 38932405, 2024). "Moreover, these CAR-Ts also managed to produce and secrete moderate and minimum levels of IL-2 upon co-cultivation with the ovarian cancer cell lines and autologous tumor cells, respectively." (PMID 38146364, 2023). "Then, nude mice with ovarian cancer were intravenously injected with IL-2 gene-expressing MSCs." (PMID 36742134, 2023). "Drerup found that IL2 receptor β-selective IL2/anti-IL2 complexes (IL2c) could preferentially stimulate effector T cells in an orthotopic mouse ID8 aggressive ovarian cancer model." (PMID 35833132, 2022). "Tregs found in ovarian cancer lesions suppress the immune response to tumor-associated antigens, which is achieved by the suppression of Interferon gamma (IFN-γ) and interleukin-2 (IL-2) secretion by the effector T cells." (PMID 36428581, 2022). "In vitro encounter with HER2+ SKOV3 ovarian carcinoma cells induced Ifng and Il2 release from all four HER2-specific CAR T cell designs regardless of co-stimulatory moiety, but designs using 4-1BB co-stimulation also induced lower cytokine levels as in CAR T cells targeting L1CAM." (PMID 33801448, 2021). "Based on our previous findings, we hypothesized that the hyporesponsiveness to IL-2, which we observed in NK cells of certain ascites from women with epithelial ovarian cancer, could be a consequence of impairment of the IL-2 and IL-15 signaling pathways." (PMID 34359872, 2021).
ovarian carcinoma (continued). "IL-15, which is similar to IL-2, can strongly increase NK cell numbers and may also enhance NK cell function in the ovarian cancer setting." (PMID 30791364, 2019). "The presence of intratumoral T cells independently associated with delayed recurrence or prolonged survival in multivariate analysis of advanced ovarian carcinoma and was related to increased expression of interferon-γ, interleukin-2, and lymphocyte-attracting chemokines within the tumor." (PMID 29423077, 2018). "Studies have shown that the antitumor function of NK cells from peripheral blood of patients with ovarian cancer can be significantly augmented by in vitro stimulation with recombinant IL-2, and that primary malignant ovarian cells are susceptible to killing by allogeneic NK lymphocytes." (PMID 28513532, 2017). "In a phase I/II study, among the 28 ovarian cancer patients treated intraperitoneally with OC/TR-armed activated T cells and IL-2, response to treatment could be assessed in 26 patients by explorative laparotomy." (PMID 27248175, 2016). "On the other hand, NK cells are known to be increased in the tumor microenvironment in ovarian cancer and have early cytolytic activity on cancer cells, and several therapies have been tested in clinical trials to recruit NK cells in ovarian cancer using IL-15 and IL-2 with limited success." (PMID 40806640, 2025). "Ovarian carcinoma ascites-derived tumor-associated T and NK cells were found to exhibit the defective expression and function of signaling proteins including decreased expression levels of TcR-zeta chains and p56 (lck), and reduced gene expression levels of IFN-γ, IL-2, and IL-4." (PMID 38932405, 2024). "Besides, elevated level of IL-5 and IL-15 in rEOC, it is very interesting to find the elevated level of IL-2 in their sera as IL-2 has promising therapeutic potential, a phase II clinical trial has shown its therapeutic benefits in platinum-resistant ovarian cancer patients." (PMID 37322531, 2023). "Furthermore, elevated level of serum cytokines IL-2, IL-5, IL-6, IL-10, and TNF-α in ovarian cancer patients, might be associated with ovarian cancer progression." (PMID 37322531, 2023). "Under T-cell activation conditions (ovarian cancer-stimulated T cells [OC-TCs] induced by PMA and ionomycin), the CM of A2780 cells (OC-CM) suppressed IFN-γ and IL-2 expression in CCRF-HSB2 cells." (PMID 40722951, 2025). "A decrease in IL-2, MCP-2/CCL8 and MCP-3/CCL7 levels was detected in both ovarian cancer cell lines with leptin administration." (PMID 37155466, 2023). "In order to investigate the effect of Treg cells on the immunity of ovarian cancer cells, we measured the concentrations of TGF-β, IFN-γ, IL-2, IL-10 and perforin in the cell supernatants using ELISA." (PMID 25376937, 2015). "C4-27z and C4opt-27z CAR T cells exclusively recognized FRα+ ovarian cancer lines, secreting high levels of Th-1 cytokines, including IFN-γ, IL-2, TNF-α and MIP-1A." (PMID 26359629, 2015). "To study the effect of Treg cells on the immunity of ovarian cancer cells, we quantified the secretion of the cytokines TGF-β, IFN-γ, IL-2, IL-10 and perforin in the different co-culture groups." (PMID 25376937, 2015). "Similar results were observed in samples isolated from human patients with colorectal, cervical and ovarian carcinoma, including the selective impairment of IFN-γ and IL-2 production in Tim-3+ CD4 T cells isolated from TILs (data not shown)." (PMID 23526963, 2013). "Treg isolated from human ovarian cancers were able to inhibit Her-2 specific CD8+ effector responses, as measured by proliferation, cytotoxicity, and IL2 and IFNγ production." (PMID 22112546, 2011). "Therefore, additional mechanistic studies on IL-2 and other possible correlations are needed to better elucidate the protection exerted by TAC on ovarian cancer seen in our study." (PMID 40647460, 2025).
ovarian carcinoma (continued). "Previous studies have demonstrated that extracellular ISG15 not only acts as an immune adjuvant to enhance the anti-tumour immunity of CD8+ T cells, but also activates NK cells and increases their production of IL-2 and IFN-γ cytokines, resulting in the proliferation of ovarian cancer CD8+ T cells." (PMID 37217923, 2023). "The second one, cited earlier, is a phase I clinical trial (NCT03932565) using fourth-generation CAR-T cells coproducing IL-7 and CCL19/IL-2 in patients with Nectin4-positive advanced malignant solid tumors such as NSCLC, breast, bladder, pancreatic and ovarian cancer." (PMID 35211124, 2022). "Favorable to the use of NK cells as therapeutic target in ovarian cancer treatment, our results showed that ascites, as a tumor environment, did not affect the expression of the CD25, CD122 and CD215 molecules, which comprise the receptors for IL-2 and IL15 cytokines." (PMID 34359872, 2021). "However, in our previous ACT trial in ovarian cancer with the same chemotherapy schedule, and high dose IL-2 (decrescendo) but without checkpoint inhibition, no patients achieved objective response despite being less heavily pretreated." (PMID 32547707, 2020).
atherosclerosis (76 papers, 2012 to 2026). A disease characterized by the build-up of fatty material and calcium deposition in the arterial wall resulting in partial or complete occlusion of the arterial lumen. "Tax induced production of cytokines like IL‐2 acts as an atherosclerosis risk factor in HTLV‐1 carriers." (PMID 40495291, 2025). "Injection of IL‐2 enhanced atherosclerosis in the Apolipoprotein E deficient (ApoE−/−) mouse model whereas the disease was reduced by injection of anti‐IL‐2 antibodies." (PMID 34569651, 2021). "Systemic administration of IL-2 to ApoE−/− mice has been shown to cause increased atherogenesis while anti-IL-2 antibodies decreased development of atherosclerosis." (PMID 22912809, 2012). "Indeed, a combination therapy with anti‐CD3 antibody and IL‐2/anti‐IL‐2 monoclonal antibody complex aimed at increasing the ratio of Tregs to pathogenic effector T cells inhibited atherosclerosis in the ApoE−/− model system." (PMID 34569651, 2021). "IL-2, like IL-6, despite its predominant pro-inflammatory functions, can exhibita dual role in the pathogenesis of atherosclerosis." (PMID 40160593, 2025). "IL-2 and TNF-α are key regulators of immune responses and have been implicated in atherosclerosis and CAD pathogenesis." (PMID 40265387, 2025). "Analysis indicated that the 9 hub genes (AKT1, HSP90AA1, SRC, GSK3β, VEGFR2, RHOA, ENO1, PKM, and IL-2) play roles in MF treatment by participating in signaling pathways related to prostate cancer, lipid and atherosclerosis, and insulin resistance." (PMID 40051434, 2025). "RYR2 regulates T-cell calcium signaling, and gain-of-function mutations lead to increased IL-2 secretion in CD4+ T cells, which is a novel immune cell infiltration-related biomarker in atherosclerosis diagnosis." (PMID 40894479, 2025). "The anti-inflammatory cytokines that were upregulated in AAA at 7, 14, and 28 days include IL-6, Il-2, IL-11, and IL-10; however, the anti-inflammatory cytokines that were upregulated in atherosclerosis include IL-6 and IL-2." (PMID 38327764, 2023). "Another proinflammatory cytokine released by Th1 cells called IL-2 is capable of accelerating atherosclerosis." (PMID 37662948, 2023). "According to prior research, intraperitoneal IL-2 injection into ApoE/mice fed an HF diet increases atherosclerosis while anti-IL-2 antibody treatment has a protective effect." (PMID 37662948, 2023). "Local delivery of IL-2 to atherosclerotic lesions in ApoE−/− mice or administration of IL-2/anti-IL-2 mAb immunocomplexes result in a decrease in atherosclerosis because Treg expansion." (PMID 36703734, 2022). "Interleukin-2(IL-2) regulates regulatory T cells and type-2 innate lymphoid cells, the two cells that are crucial for atherosclerosis and myocardial healing." (PMID 36467726, 2022). "In contrast, local delivery of IL‐2 to plaques attenuated atherosclerosis development by activating Tregs." (PMID 34569651, 2021). "Cytokines produced by B cells can enhance immunomodulation during chronic inflammation; for example, TNF-α, IL-2, and IL-10 produced by B2 cells promoted atherosclerosis." (PMID 34522782, 2021). "In line with this idea, we found that the combination treatment with anti-CD3 antibodies and IL-2 complexes was effective in expanding Treg with activated phenotype and preventing atherosclerosis development in Apoe−/− mice." (PMID 34945203, 2021). "In Apoe−/− mice, local delivery of IL-2 to atherosclerotic lesions or treatment with IL-2/anti-IL-2 mAb immunocomplexes lead to a reduction in atherosclerosis due to Treg expansion." (PMID 33805071, 2021). "Clinical trials are in course in which the therapeutic potential of low-dose IL-2 is being evaluated as a Treg-inducer for inflammatory diseases, including atherosclerosis." (PMID 32395119, 2020). "In this regard, cholesterol attenuates IL‐2 signaling, and induces Bcl6 expression and Tfh differentiation in the context of atherosclerosis." (PMID 33230950, 2020).
atherosclerosis (continued). "It has also been shown that intraperitoneal injection of IL-2 into ApoE−/−mice fed with a high-fat diet enhances atherosclerosis, while IL-2 antibody treatment has a protective effect, indicating that IL-2 is atherogenic." (PMID 32899258, 2020). "Recent studies have proposed that elevated levels of IL-2 indicate intensified T cell response to different antigens, which are assumed to be critical in the promotion of atherosclerosis 7,8." (PMID 30090212, 2018). "It is unclear how IL-2 and IL-12 upregulation influence atherosclerosis in ApoE−/−Adamts4−/− mice and further studies are needed to clarify their roles." (PMID 27491335, 2016). "P.gingivalis can suppress the accumulation of IL-2 and attenuate T cells proliferation to alter adaptive immune responses in the process of atherosclerosis." (PMID 24466164, 2014). "The main pathways involved include the focal adhesion‐PI3K‐Akt‐mTOR‐signaling pathway; AhR; fluid shear stress and atherosclerosis; protein processing in endoplasmic reticulum; thermogenesis; adipogenesis; and several inflammatory‐related pathways (IL‐5, IL‐2, TGF‐β receptor, and IL‐6 signaling)." (PMID 41169019, 2025). "Persistent low-grade inflammation, characterized by moderate increases in circulating pro-inflammatory cytokines (C-reactive protein: CRP; interleukins (IL): IL-6, IL-2, IL-7, IL-8, etc.), plays a significant role in all atherosclerosis formation and progression phases." (PMID 40428891, 2025). "This idea is supported by our previous study in hypercholesterolemic Apoe−/− mice showing that administration of anti-CD3 antibodies and IL-2 complexes dramatically expanded Tregs by reducing Teff responses and potently attenuated the development of atherosclerosis." (PMID 39993786, 2025). "Several immunological therapies, such as the use of an FcR-nonbinding anti-CD3 monoclonal antibody, an IL-2/anti-IL-2 monoclonal antibody complex, their combination, and the active form of vitamin D3, have been shown to be valid approaches to prevent atherosclerosis by increasing Treg numbers." (PMID 36405994, 2022). "In an animal experiment, cytokine therapy with IL-2/anti-IL-2 monoclonal antibody complexes could attenuate the development and progression of atherosclerosis by increasing CD4+CD25+Foxp3+ regulatory T cells in apolipoprotein E-deficient mice." (PMID 36299596, 2022). "Therefore, it has been proposed that the alteration of adaptive immune response and the fluctuation of IL-2 levels are responsible for the internal inflammatory state of atherosclerosis." (PMID 36467726, 2022). "IL2 is an inflammatory factor that is related to the formation of atherosclerosis." (PMID 36212940, 2022). "Consequently, cholesterol-mediated attenuation of IL-2 signaling, along with the increased IL-6R and Bcl6 expression, initiate Tfh differentiation in the context of atherosclerosis." (PMID 33465845, 2021). "However, low doses of IL-2 give a strong result in the atherosclerosis treatment, due to the selective expansion of Tregs with essential sensitivity to IL-2." (PMID 34445084, 2021). "Furthermore, clinical trials of low-dose IL-2 therapy were shown to reduce atherosclerosis by regulatory T cell-mediated suppression of inflammation." (PMID 33383733, 2020). "The detected lower level of IL-2 in CAE may suggest attenuated positive feedback of macrophage activation different from atherosclerosis, i.e., attenuated TH1 response, but macrophages still had an alternative trigger for direct activation." (PMID 29337902, 2018). "IL-2 and pSTAT5 are also potent inhibitors of Tfh differentiation, suggesting that cholesterol-mediated IL-2 signaling attenuation, together with increased IL-6R and Bcl6 expression, initiate Tfh differentiation in context of atherosclerosis." (PMID 29545616, 2018). "In our study, we found lower levels of IL-2 in the CAE group when compared to atherosclerosis." (PMID 29337902, 2018).